MKI67 (marker of proliferation Ki-67)
Diseases named in the same sentence as MKI67 in open-access papers (continued):
Sharing a sentence is not in itself a finding about the gene and the disease.
esophageal squamous cell carcinoma (18 papers, 2012 to 2025). Esophageal squamous cell carcinoma (ESCC) is a type of esophageal carcinoma (EC) that can affect any part of the esophagus, but is usually located in the upper or middle third. "MKI67, also known as Ki-67, acts as a biological surfactant to disperse mitotic chromosomes, which has been demonstrated in various carcinomas, including gastric, esophageal, colonic, rectal, and esophageal squamous cell carcinoma." (PMID 33061942, 2020).
cholangiocarcinoma (17 papers, 2013 to 2025). A carcinoma that arises from the intrahepatic biliary tree (intrahepatic cholangiocarcinoma) or from the junction, or adjacent to the junction, of the right and left hepatic ducts (hilar cholangiocarcinoma). "The cells in the cholangiocarcinoma tissue were primarily classified into the following subpopulations: Monocytes, Dendritic cells, Epithelial cells, NK cells, T cells, MKI67 + T cells, Endothelial cells, Macrophages, and Fibroblasts." (PMID 40959663, 2025). "However, MKI67 expression was not related to the infiltration degrees of CD4+ T cells, CD8+ T cells, B cells, macrophages, DCs, or neutrophils within cholangiocarcinoma (CHOL)." (PMID 34724892, 2021).
cutaneous melanoma (16 papers, 2010 to 2025). A primary melanoma arising from atypical melanocytes in the skin. "MKI67 levels decreased significantly in skin cutaneous melanoma (SKCM) relative to matched noncarcinoma samples." (PMID 34724892, 2021).
liver fibrosis (16 papers, 2013 to 2025). "Additionally, other markers exclusive to the proliferating cells, such as MKI67 and PCNA, have been implicated in fibrotic conditions, including IPF, hepatic fibrosis, and cancer." (PMID 38727265, 2024).
influenza (15 papers, 2016 to 2024). An acute viral infection of the respiratory tract, occurring in isolated cases, in epidemics, or in pandemics; it is caused by serologically different strains of viruses (influenzaviruses) designated A, B, and C, has a 3-day incubation period, and usually lasts for 3 to 10 days. "Cluster IV contained several immunoglobulin genes, in addition to MKI67 (Ki67), TOP2A and BIRC5 (Survivin), which are associated with proliferation, likely representing a plasmablast signature as has been reported at Day 7 after immunization with the influenza vaccine." (PMID 33720973, 2021).
teratoma (15 papers, 2008 to 2026). A non-seminomatous germ cell tumor characterized by the presence of various tissues which correspond to the different germinal layers (endoderm, mesoderm, and ectoderm). "Importantly, post-transplantation analysis of differentiated iTPCs found that only 5% were positive for Marker of proliferation Ki-67 (Ki-67), indicating that proliferation amongst these cells did not present teratoma concerns and lacked initial tumorigenic markers." (PMID 37239940, 2023).
Hodgkins lymphoma (14 papers, 1996 to 2025). A heterogeneous group of malignant lymphoid neoplasms of B-cell origin characterized histologically by the presence of Hodgkin and Reed-Sternberg (HRS) cells in the vast majority of cases. "Ki‐67 protein, encoded by the MKI67 gene located on chromosome 10q25‐ter, was first identified as an antigen in Hodgkin lymphoma cell nuclei." (PMID 35332684, 2022).
Sepsis (14 papers, 2018 to 2025). Sepsis is defined as life-threatening organ dysfunction caused by a dysregulated host response to infection. "MKI67, a classical proliferation marker, may have a dual role in the sepsis immune microenvironment: high expression may occur during early excessive activation of immune cells, while decreased proliferative capacity may accompany the late immunosuppressive state." (PMID 41246299, 2025). "This study obtained a total of 4 biomarkers (MYO10, SULT1B1, MKI67, and CREB5), and the analysis of nomogram showed that the biomarkers had good clinical predictive value to sepsis." (PMID 41246299, 2025). "The potential mechanisms of the four biomarkers (MYO10, SULT1B1, MKI67, CREB5) identified in this study in sepsis can be preliminarily interpreted through their known functions and related pathways." (PMID 41246299, 2025). "This study identified 4 biomarkers, namely MYO10, SULT1B1, MKI67, and CREB5 and explored the pathogenesis of sepsis, providing new insights for potential treatment strategies by integrating transcriptomic data and single-cell analysis." (PMID 41246299, 2025). "The RT-qPCR results showed the expression of MYO10, SULT1B1, MKI67, and CREB5 had significant differences between controls and sepsis samples (P < 0.05)." (PMID 41246299, 2025). "In summary, these biomarkers may be involved in sepsis through mechanisms related to cell cycle regulation (MYO10, MKI67), metabolic reprogramming (SULT1B1), and inflammatory signal transduction (CREB5)." (PMID 41246299, 2025).
acromegaly (13 papers, 2019 to 2026). Acromegaly is an acquired disorder related to excessive production of growth hormone (GH) and characterized by progressive somatic disfigurement (mainly involving the face and extremities) and systemic manifestations. "Differences between transcriptomic groups were also observed in expression levels of proliferation-related genes CCND1, CDKN1B, and MKI67 and genes involved in cell signaling TGFB1 and STAT3 that all have a reported role in acromegaly patients’ outcome." (PMID 36497102, 2022). "Tumor expression of particular genes was found of prognostic/predictive value in acromegaly patients, These genes include basically CDH1 and SSTR2 but also CDKN1B SNAI2, FLNA, ARRB1, SNAI1 RORC ESRP1, and MKI67." (PMID 39497133, 2024).
asthma (12 papers, 2013 to 2025). "MKI67 suppression in fibroblasts might indicate the loss of proliferative mesenchymal phenotype or population in asthma with specific enrichment in Th2-high phenotype only." (PMID 34088958, 2021). "Several genes such as SERPINE1, GPRC5A, SFN, ABCA1, MKI67, and RRM2 have been found to be downregulated in severe uncontrolled asthma using PBMCs and, therefore, potential biomarkers." (PMID 36294997, 2022). "Validation of the gene expression in PBMC of locally recruited asthma patients showed that SERPINE1, GPRC5A, SFN, ABCA1, MKI67, and RRM2 were downregulated in severe uncontrolled asthma." (PMID 34088958, 2021). "In our cohort, MKI67 was upregulated in the PBMCs of nonsevere but significantly downregulated in severe asthmatic patients and uncontrolled asthma (ACT < 20) compared to healthy controls." (PMID 34088958, 2021). "Based on that MKI67 mRNA expression in PBMC can give an accurate impression if the immune cells are in active proliferative phase close to antigen exposure and if the immune cells are impaired like in severe asthma by the disease or in response to immune suppression like steroids." (PMID 34088958, 2021). "MKI67 and SERPINE1 expression was higher in nonsevere asthma but was downregulated in severe asthmatics compared to healthy controls (p < 0.05)." (PMID 34088958, 2021). "MKI67 and SERPINE1 expression was higher in nonsevere asthma but was downregulated in severe asthmatics compared to healthy controls." (PMID 34088958, 2021).
ischemic stroke (12 papers, 2017 to 2025). A stroke disorder caused by obstruction of blood flow to the brain, due to thrombotic (local blood clot formation) or embolic (due to a blood clot or other material traveling from another site) event. "In this study, we identified 3 distinct ischemic stroke-associated microglia (ISAM) specifically marked with MKI67 (MG4), OASL (MG5), and CH25H (MG6), respectively." (PMID 37183260, 2023). "We identified a relatively homeostatic subcluster with enhanced antigen processing and three “ischemic stroke associated microglia” (ISAM): MKI67+, CH25H+ and OASL+ subclusters." (PMID 37183260, 2023). "Ultimately, seven downregulated hub genes (including Mki67, Cdk1, Tpx2, Cenpf, Ccnb2, Prc1, and Top2a) were identified as key genes regulated by EA treatment in ischemic stroke by PCR validation." (PMID 34566862, 2021). "Therefore, EA might exert neuroprotection in ischemic stroke by inhibiting reactive astrocyte and microglial (Mki67, Top2a, and Cenpf as markers) proliferation." (PMID 34566862, 2021).
pilocytic astrocytoma (12 papers, 2013 to 2025). Pilocytic astrocytoma is a rare subtype of low-grade glioma of the central nervous system characterized by a well circumscribed, often cystic, brain tumor with a discrete mural nodule and long, hair-like projections that extend from the neoplastic astrocytes. "MKI67 levels as a surrogate for proliferation were higher than in pilocytic astrocytoma (PA), but lower than the GBM subgroups (online resource)." (PMID 34417833, 2021).
steatosis (12 papers, 2013 to 2025). Increased lipid within the cytoplasm of cells. "Increased abundances of Smpd3, Dtl, Cdc6, Mki67, and Top2a were detected after 14 and 42 days of feeding WD, which was consistent with the initiation and advanced phases of steatosis in hepAGT +/+ mice." (PMID 40687776, 2025). "By integrating data from the two RNA sequencing analyses, we identified five molecules related to cell division: Smpd3, Dtl, Cdc6, Mki67, and Top2a, as key mediators in suppressing WD-induced steatosis in hepAGT −/− mice." (PMID 40687776, 2025).
ZIKV infection (12 papers, 2017 to 2025). "Proteins previously identified to be differentially expressed during ZIKV infection include GAP43, DCX, PTPRZ1, ASNS, SLC3A2 and MKI67." (PMID 32873194, 2020).
follicular carcinoma (10 papers, 2014 to 2025). "To prove this effect with follicular thyroid cancer cells and in the context of μg, we searched for cellular markers for proliferation such as the Ki-67 protein (encoded by MKI67)." (PMID 32033410, 2020). "We finally constructed glycolysis risk score (GRS) predictive models based on four targeting genes (ADM, CD44, MKI67 and TYMS), which were highly upregulated in tumor samples, including papillary and follicular thyroid cancers." (PMID 35528004, 2022).
pancreatic (10 papers, 2011 to 2026). "Although EGFR signaling and cell proliferation, as represented by nuclear EGR1 and MKI67, were significantly induced in AGR2+/- mice with pancreatitis on Day 1, the levels were 65% and 75% lower, respectively, than wild-type AGR2+/+ mice." (PMID 27764193, 2016). "AG1478-treated AGR2+/- heterozygotes with pancreatitis also exhibited significantly reduced nuclear EGR1 compared to AG1478-untreated heterozygotes, but MKI67 was not significantly affected." (PMID 27764193, 2016).
gallbladder cancer (9 papers, 2013 to 2026). "We analyzed the differentially expressed genes and the correlation between these genes with MKI67, and showed that KIF11 is one of the major upregulated regulators of proliferation in gallbladder cancer (GBC)." (PMID 33613109, 2021).
dengue (8 papers, 2010 to 2025). "While their roles in dengue remain uncharacterized, MKI67’s association with proliferating cells (e.g., plasmablasts) and MCC’s NF-κB modulation by MCC suggest a potential involvement in viral replication or immune dysregulation." (PMID 41583452, 2025).
kidney cancer (7 papers, 2014 to 2023). Primary or metastatic malignant neoplasm involving the kidney. "A study found that psoralen could slow the progression of kidney cancer by inhibiting the expression of MKI67, PCNA, MMP2 and MMP9 as well as the proliferation, invasion, and migration of kidney cancer cells HTB-47 and CRL-1932." (PMID 36627680, 2023).
pterygium (7 papers, 2009 to 2021). A wedge-shaped fibrovascular lesion arising from the bulbar conjunctiva and extending to the cornea. "Consistent with this, MKI67, which encodes a marker of cell proliferation, is downregulated in pterygium." (PMID 34769520, 2021).
neutropenia (6 papers, 2015 to 2024). A decrease in the number of neutrophils found in the blood. "Recent studies show that MKI67 and TOP2A were contained within a network of genes that are upregulated in NK-cell repertoires in patients with neutropenia, which is associated with apoptosis and cell cycle." (PMID 37834393, 2023).
peritoneal cancer (6 papers, 2016 to 2026). A peritoneum cancer that is located in the inside of the abdomen. "Deregulation of the expression of BAG1, CCNB1, MKI67, and MYBL2 was documented in PC biopsies, suggesting that growth and cell proliferation pathways are disturbed, a feature of malignant transformation in ovarian and peritoneal cancer that has been widely documented in the literature." (PMID 27542596, 2016).
brain cancer (5 papers, 2015 to 2023). A primary or metastatic malignant neoplasm affecting the brain. "In addition, other datasets also showed decreased levels of MKI67 mRNA expression in CNS and brain cancers and BC, kidney, and leukaemia cancers." (PMID 34724892, 2021).
Chronic colitis (5 papers, 2016 to 2026). A chronic inflammatory disease of the large intestine (colon, cecum and rectum). "In contrast, the percentage of cluster 2 (Mki67+ neutrophils) was found to be increased in both the acute and chronic colitis models." (PMID 36922861, 2023).
Infertility (5 papers, 2019 to 2026). "Compared to wild-type mice, the expression of MKI67 in GCs is significantly lower than in GC-specific steroidogenic factor 1 deficiency mice with impaired follicle development and infertility." (PMID 31671754, 2019).
large cell lymphomas (5 papers, 2023 to 2026). "Clusters 3.4 and 3.6 also featured upregulation of genes implicated in large cell lymphomas, and notably overlapping with several genes enriched in RT tumors compared to matched CLL precursors, including Birc5, Cdk1, Mki67, and Npm1." (PMID 36609611, 2023).
adrenal carcinoma (4 papers, 2017 to 2022). A carcinoma involving a adrenal gland. "We added the expression levels of the Marker of Proliferation Ki-67 (MKI67) gene, as its expression is a keystone marker of proliferation widely used in adrenal cancer prognosis." (PMID 29283884, 2017).
heart failure (4 papers, 2013 to 2025). Inability of the heart to pump blood at an adequate rate to meet tissue metabolic requirements. "Violin plots illustrating inter-subpopulation disparities indicated that C0 NAP1L1+ TCs and C2 MKI67+ TCs possessed considerably elevated heart failure scores, whereas C1 CA2+ TCs demonstrated moderate values, and C3 ITLN1+ TCs displayed the lowest scores." (PMID 40842994, 2025). "The cardiac failure scores were significantly elevated in C0 NAP1L1+ TCs (stage II), C1 CA2+ TCs (stage II), and C2 MKI67+ TCs (stage II)." (PMID 40842994, 2025). "We additionally illustrated the expression pattern and density of heart failure scores among subpopulations by UMAP plots, indicating that peak values are primarily concentrated in C0 NAP1L1+ TCs and C2 MKI67+ TCs." (PMID 40842994, 2025). "Heart failure scores were elevated in C0 NAP1L1+ TCs (G1), C0 NAP1L1+ TCs (G2/M), C0 NAP1L1+ TCs (S), C2 MKI67+ TCs (G2/M), and C2 MKI67+ TCs (S)." (PMID 40842994, 2025). "Utilizing this gene set, we evaluated all tumor cell subpopulations and discovered that C2 MKI67+ TCs—predominantly in the G2/M and S phases—demonstrated significantly heightened heart failure scores, whereas their cardiac fibrosis scores were not substantially elevated." (PMID 40842994, 2025). "Alternatively, it may suggest that C2 MKI67+ TCs contribute indirectly to the advancement of heart failure by the production of factors or exosomes, rather than acting as primary instigators of myocardial fibrosis." (PMID 40842994, 2025).
pneumonia (4 papers, 2020 to 2025). An acute, acute and chronic, or chronic inflammation focally or diffusely affecting the lung parenchyma, caused by an infection in one or both of the lungs (by bacteria, viruses, fungi, or mycoplasma.). "The expression of PDCD1(PD‐1) and MKI67 in acute pneumonia was analyzed." (PMID 34841705, 2021).
autism (3 papers, 2021 to 2024). Persistent deficits in social interaction and communication and interaction as well as a markedly restricted repertoire of activity and interest as well as repetitive patterns of behavior. "MKI67 gene expression analysis (a marker for cell proliferation) revealed ~75% reduced expression of MKI67 in autism vs. controls." (PMID 38994948, 2024). "Expression analysis for DCX transcript, a marker of neuronal migration, revealed 80% reduced expression in autism, while MKI67 expression level was the same in both groups." (PMID 38994948, 2024). "However, MKI67, a marker for cell proliferation, revealed a significantly increased expression in NSCs of patients with autism (p = 0.048)." (PMID 38994948, 2024).
cardiomyopathy (3 papers, 2021 to 2023). A disease of the heart muscle or myocardium proper. "Results of the current study showed that MKI67 induces cardiomyopathy, and BDKRB2 inhibits the disorder." (PMID 34236536, 2021).
HCMV infection (3 papers, 2019 to 2024). "Surprisingly, HCMV infection downregulated the mRNA expression levels of the proliferation marker Ki67 (MKi67) exclusively in RPTECs (P < 0.01) but not in HFFs or ARPE-19 cells." (PMID 38459109, 2024).
latent infection (3 papers, 2014 to 2023). "The cell proliferation marker MKI67 as well as genes involved in G1-S and G2-M transition, such as CDK1, CDK2, CCNE2, PRIM2, AKT1, and FOXM1, were significantly downregulated in latent infection compared to actively infected cells." (PMID 38038477, 2023).
Hepatic steatosis (2 papers, 2022 to 2025). Steatosis is a term used to denote lipid accumulation within hepatocytes. "The present study identified five genes (Smpd3, Dtl, Cdc6, Top2a, and Mki67) as potential mediators in the development of WD-induced liver steatosis." (PMID 40687776, 2025). "While our findings and previous literature suggest potential mechanisms by which Smpd3, Dtl, Cdc6, Top2a, and Mki67 contribute to liver steatosis, further study is needed to clarify their precise roles." (PMID 40687776, 2025).
Hepatitis (2 papers, 2020 to 2022). Inflammation of the liver. "Here, we show that these cells are proliferating at a higher level in ConA-induced hepatitis as evidenced by the increase in expression of Mki67." (PMID 35720411, 2022).
intracranial aneurysm (2 papers, 2020 to 2025). "MKI67 functions as a critical m6A methylation-regulated hub target,mediating inflammation associated with intracranial aneurysm." (PMID 40521894, 2025).
neuropathies (2 papers, 2024 to 2025). "In one study, expression levels of 2 genes(MKI67 and SLC22A8) were associated with neuropathies in rats receiving linezolid." (PMID 38939039, 2024).
rheumatoid arthritis (2 papers, 2009 to 2022). A chronic, systemic autoimmune disorder characterized by inflammation in the synovial membranes and articular surfaces. "Moreover, the Mki67 cluster had fewer differentially activated pathways, mainly grouped into oxygen transport and rheumatoid arthritis immunity." (PMID 35185928, 2022).
testicular seminoma (2 papers, 2023 to 2025). A malignant germ cell tumor arising from the testis. "In testicular seminoma, miR-665 suppresses the expression of MKI67, a hub gene that promotes cell proliferation, migration, and invasion in testicular seminoma." (PMID 37894282, 2023).
acute kidney injury (1 paper, 2023). Sudden and sustained deterioration of the kidney function characterized by decreased glomerular filtration rate, increased serum creatinine or oliguria. "MKi67 and TOP2A have been shown to modulate DNA replication of cell cycle, and participate in renal repair after acute kidney injury." (PMID 37460555, 2023).